CILP2 (cartilage intermediate layer protein 2)
Description:
May play a role in cartilage scaffolding.
Synonyms: MGC45771; CLIP-2
Tractability: Antibody: UniProt places it where antibodies can reach, with high confidence; UniProt predicts a signal peptide or a membrane-spanning region; its Gene Ontology location is reachable by antibodies, with medium confidence.
Gene: Protein-coding gene on chromosome 19 (19,538,248 to 19,546,659, forward strand). Ensembl gene ENSG00000160161.
Subcellular location: Secreted, extracellular space, extracellular matrix
Gene Ontology:
Molecular function: alkaline phosphatase activity; dinucleotide phosphatase activity
Cellular component: extracellular exosome; non-collagenous component of interstitial matrix
Genetic constraint (gnomAD): Loss-of-function variants: 36 observed, 35.77 expected, observed/expected ratio (o/e) 1.01, 90% interval 0.77 to 1.33. The upper end of that interval is the gene's LOEUF score, 1.33, which puts it in group 5 of 6, group 1 being the genes least tolerant of losing a copy. Missense variants: 1,735 observed, 1,557.7 expected, observed/expected ratio (o/e) 1.11, 90% interval 1.07 to 1.16. Synonymous variants: 780 observed, 677.18 expected, observed/expected ratio (o/e) 1.15, 90% interval 1.09 to 1.22.
Homologues: Orthologues: chimpanzee CILP2 (99% identical), macaque CILP2 (96% identical), pig CILP2 (89% identical), dog CILP2 (89% identical), guinea pig CILP2 (80% identical), rat Cilp2 (80% identical), mouse Cilp2 (79% identical), zebrafish cilp2 (55% identical), tropical clawed frog cilp2 (54% identical). Paralogues in human: CILP (49% identical).
Diseases named in the same sentence as CILP2 in open-access papers:
CILP2 is named in the same sentence as 76 diseases in open-access papers, as found by Europe PMC text mining. Sharing a sentence is not in itself a finding about the gene and the disease. The quoted sentences say what the papers report.
diabetes (7 papers, 2016 to 2026). "As a genotype-environment interaction was considered, G6 (CILP2 G-T) carriers and diabetes increased the risk of hyperlipidemia." (PMID 32568739, 2020). "Furthermore, CILP2 is a susceptibility gene for diabetes and is closely related to the occurrence and development of diabetes." (PMID 38136386, 2023). "Furthermore, a meta-analysis of 39 multiethnic type 2 diabetes mellitus (T2DM) association studies has implicated that CILP-2 confers the risk susceptibility for T2DM." (PMID 30896018, 2019). "These include CCND2, CILP2, PBX4, SH2B3, SLC6A4, TCF7 and KLF14, which have polymorphisms associated with diabetes risk." (PMID 27029739, 2016). "Notably, circulating CILP-2 levels in the studied population were gradually elevated from normal subjects to IGT (pre-diabetes) and to T2DM, following increased blood glucose levels." (PMID 30896018, 2019). "Therefore, we believe that hyperglycemia increases the expression and secretion of CILP-2, which in turn promote glyconeogenesis and lead to a vicious cycle to promote the progression of diabetes." (PMID 30896018, 2019). "Functionally, CILP2 is upregulated by metabolic stress, including high glucose and oxidatively modified LDL (oxLDL), and actively contributes to pathologies such as dyslipidemia, diabetes, and sarcopenia by impairing glucose metabolism and mitochondrial function." (PMID 41594707, 2026).
dyslipidemia (7 papers, 2016 to 2026). "This aligns with previous research suggesting that CILP2 is associated with metabolic syndrome [S34]." (PMID 39385717, 2024). "The SNP of rs16996148 in NCAN-CILP2 or NCAN/CILP2/PBX4 was significantly associated with dyslipidemia in the midlands and east of the Chinese Han population." (PMID 32568739, 2020). "Besides, pre-B-cell leukemia transcription factor 4 (PBX4/CILP2 locus) and B-cell CLL/lymphoma 3 genes are considered to be the association factors for dyslipidemia." (PMID 37384286, 2023). "Furthermore, a number of genes within the RNO16 differential segment associated with metabolic syndrome components in human studies showed polymorphisms between SHR and BN-Lx (including Lpl, Nrg3, Pbx4, Cilp2, and Stab1)." (PMID 27031336, 2016). "We also found that circulating CILP-2 was correlated significantly with parameters of adiposity (WHR), dyslipidemia (TG and HDL-C), blood glucose and IR (HOMA-IR)." (PMID 30896018, 2019). "Therefore, we propose that elevated circulating CILP2 in patients with CHD may be a defensive response against metabolic stress, such as dyslipidemia, or resistance to atherosclerosis." (PMID 33204392, 2020).
type 2 diabetes (6 papers, 2015 to 2021). "Genetic association studies have implicated that cartilage intermediate layer protein 2 (CILP-2) confers the risk susceptibility for type 2 diabetes (T2DM)." (PMID 30896018, 2019).
colorectal cancer (4 papers, 2020 to 2026). A primary or metastatic malignant neoplasm that affects the colon or rectum. "Recent studies have identified CILP2 as a prognostic biomarker associated with immune infiltration in colorectal cancer." (PMID 38136386, 2023). "During the process of literature review, we have discovered that the novel protein-coding gene, cartilage intermediate layer protein 2, has been partially associated with colorectal cancer in several studies." (PMID 38136386, 2023). "More recently, CILP2 has emerged as an oncoprotein, overexpressed in multiple cancers, including pancreatic ductal adenocarcinoma and colorectal cancer." (PMID 41594707, 2026). "However, limited information is available regarding the role of CILP2 in cancers, with only one study reporting that it may have served as a prognostic marker for colorectal cancer." (PMID 38136386, 2023).
Insulin resistance (4 papers, 2019 to 2024). Increased resistance towards insulin, that is, diminished effectiveness of insulin in reducing blood glucose levels. "Bioinformatics analysis showed that the genes related to CILP2 are primarily associated with lipid metabolism and insulin resistance." (PMID 35757483, 2022). "In our previous study, we found that CILP2 was associated with insulin resistance." (PMID 35757483, 2022). "Bioinformatic analysis of CILP2 protein interactions has indicated that CILP2‐related genes are involved mainly in energy metabolism, skeletal muscle phylogenesis and insulin resistance (IR)." (PMID 39385717, 2024). "We previously reported that CILP2 is a secretory protein and is highly expressed in patients with insulin resistance." (PMID 35757483, 2022). "Circulating CILP2 levels (measured by ELISA) were compared to various insulin resistance- and atherosclerosis-related parameters in normal subjects and newly diagnosed CHD patients." (PMID 33204392, 2020). "However, whether CILP-2 plays a role in the regulation of glucose homeostasis and insulin resistance (IR) is unknown." (PMID 30896018, 2019). "However, it is still unknown whether CILP-2 is involved in the regulation of glucose homeostasis and insulin resistance (IR)." (PMID 30896018, 2019). "We found that circulating CILP2 levels had a progressive increase from normal to impaired glucose tolerance (IGT) and then to diabetes, which was correlated with insulin resistance (IR) and obesity." (PMID 33204392, 2020). "Circulating CILP2 correlated positively with waist-hip ratio (WHR), total cholesterol (TC), low-density lipoprotein cholesterol (LDL-C), HbA1c, homeostasis model assessment of insulin resistance (HOMA-IR), and Gensini scores." (PMID 33204392, 2020).
Obesity (4 papers, 2019 to 2023). Accumulation of substantial excess body fat. "Compared with the normal weight group, the levels of serum CILP2 in overweight and obese groups were significantly higher, suggesting a potential association between CILP2 and obesity." (PMID 35757483, 2022). "In order to further explore the relationship between CILP2 and obesity, we conducted an online bioinformatics analysis." (PMID 35757483, 2022). "Multivariate linear regression analysis was used to explore the relationship between CILP2 and obesity." (PMID 35757483, 2022). "Since obesity is closely related to the disorders of glucose and lipid metabolism, we explored the relationship between human circulating CILP2 levels and overweight/obesity in this study." (PMID 35757483, 2022). "The aim of this study was to investigate the relationship between circulating CILP2 levels and obesity based on body mass index (BMI)." (PMID 35757483, 2022). "Further studies are needed to explore the pathophysiological role of CILP2 in obesity and its effect on glucose and lipid metabolism." (PMID 35757483, 2022). "Furthermore, PIK3C2G, FIBIN, CHRNA1, NPNT, MEOX1, and POU2F2 linked obesity and lung cancer, while PTPRQ, SSUH2, CILP2, CDH2, ABCA12, CPXM1, and L1CAM linked hypertension and lung cancer." (PMID 36685671, 2023). "More detailed research is needed to explore the effect of tissue CILP2 level on obesity." (PMID 35757483, 2022). "We speculate that the decreased expression of CILP2 in adipose tissue is a compensatory effect in response to the occurrence of obesity." (PMID 35757483, 2022). "Furthermore, CILP2 was markedly correlated with the parameters of obesity (WHR), IR (HOMA-IR), glucose metabolism (HbA1c), and atherosclerosis (TC, LDL-C, HDL-C, and Gensini score) in our study population." (PMID 33204392, 2020). "In addition, our study is a cross-sectional study without considering the causal relationship between serum CILP2 levels and obesity." (PMID 35757483, 2022). "We speculate that CILP2 may attribute to metabolic disorders in obesity." (PMID 35757483, 2022). "However, the correlation between CILP2 and obesity remains unknown." (PMID 35757483, 2022). "Further investigations are needed to explore whether CILP2 can affect lipid metabolism through CD36 in adipose tissue, skeletal muscle, and other tissues under obesity." (PMID 35757483, 2022).
osteoarthritis (4 papers, 2019 to 2025). A noninflammatory degenerative joint disease occurring chiefly in older persons, characterized by degeneration of the articular cartilage, hypertrophy of bone at the margins and changes in the synovial membrane. "This suggested that increased CILP2 levels may be linked to a higher risk of osteoarthritis, particularly in the degenerative changes observed in the knee joint." (PMID 40996951, 2025). "Another study, which analyzed osteoarthritis patients who underwent total knee replacement surgery, found significantly elevated CILP2 levels in the joint cartilage post-surgery." (PMID 40996951, 2025). "An early basic study utilizing an osteoarthritis mouse model found that as cartilage degraded, the expression and protein levels of the CILP2 gene were markedly downregulated." (PMID 40996951, 2025). "Previous studies have focused on the potential role of CILP2 in osteoarthritis." (PMID 40996951, 2025). "Since CILP-2 rather than CILP-1 has been suggested to be related to the progression of osteoarthritis, some diagnostic value has been attributed to it." (PMID 39506696, 2024). "Moreover, a proteomics study confirmed that CILP2 gene expression was significantly elevated in the cartilage of osteoarthritis patients compared to non-osteoarthritis individuals, indicating that CILP2 could potentially serve as a predictive marker for the onset of osteoarthritis." (PMID 40996951, 2025).
sarcopenia (4 papers, 2024 to 2026). Progressive decline in muscle mass due to aging which results in decreased functional capacity of muscles. "This study demonstrates a significant association between elevated CILP2 levels and reduced glycogen synthesis and protein degradation in a muscular dystrophy model, as observed in patients with sarcopenia and aged mice." (PMID 39385717, 2024). "It has been reported that CILP2 affect sarcopenia and hypertrophic scar by antagonizing Wnt signaling pathway, and reducing the ubiquitination of ACLY, respectively." (PMID 41244802, 2025). "Initially, the expression levels of CILP2 were assessed in elderly mice and patients with sarcopenia." (PMID 39385717, 2024). "This study identified CILP2 as a potential biological target for glucose metabolism in the treatment of sarcopenia, which should be prioritized in future research." (PMID 39385717, 2024). "Thus, further research is required to elucidate the signaling pathways influencing CILP2 and understand the role of pro‐inflammatory chemokines and biomarkers of cellular senescence in both human and mouse models of sarcopenia." (PMID 40837039, 2025). "We synthesized CeNPs that exhibit considerable biocompatibility and anti‐senescent effects in sarcopenia through their ability to scavenge ROS and downregulate CILP2 in muscle tissues, which may reduce SERPINE1 and phospho‐p21 expression." (PMID 40837039, 2025). "Our findings also suggest that CeNPs may exert an immunomodulatory effect in sarcopenia through their ROS scavenging ability and downregulation of CILP2 in muscle tissue." (PMID 40837039, 2025). "Importantly, the inhibition of Cilp2 has been shown to improve mitochondrial dysfunction in sarcopenia via the WNT signaling pathway." (PMID 41244802, 2025). "Consequently, inhibiting CILP2 signalling enhances glucose metabolism and mitochondrial function, making it a potential therapeutic target for sarcopenia." (PMID 39385717, 2024). "Owing to the complexity and interrelationships of these molecular pathways, it remains unclear whether CILP2 plays a role in sarcopenia through the regulation of glucose homeostasis and IR." (PMID 39385717, 2024). "We further conducted in vivo studies to explore whether CILP2 knockout promotes myogenic differentiation and glucose metabolism and alleviates sarcopenia." (PMID 39385717, 2024). "We evaluated CILP2 expression patterns during ageing and the progression of sarcopenia to determine whether CILP2 is involved in skeletal muscle regeneration and glucose metabolism." (PMID 39385717, 2024). "Notably, our groundbreaking discovery indicates that CILP2 is a promising biomarker for sarcopenia." (PMID 39385717, 2024). "Targeting CILP2 inhibition could offer potential therapeutic benefits for sarcopenia." (PMID 39385717, 2024). "CILP2 expression was significantly elevated in the skeletal muscle of patients with sarcopenia compared to those without." (PMID 39385717, 2024).
hyperlipidemia (3 papers, 2020 to 2022). "Another study in Southwest China demonstrated that the genotype and allele frequency of SNP locus located in CILP2 are significantly different between patients with hyperlipidemia and normal subjects." (PMID 35757483, 2022). "The haplotype-haplotype interaction showed that G10 (MAU2 G-A-G-C) and G6 (CILP2 G-T) carriers could reduce the risk of hyperlipidemia compared with G10 or G6 carriers." (PMID 32568739, 2020). "In conclusion, this study shows potential interactions among the NCAN, TM6SF2, CILP2, PBX4, SUGP1 and MAU2, environment and serum lipid levels in hyperlipidemia subjects." (PMID 32568739, 2020). "The genotypic and allelic frequencies of 12 SNPs in the NCAN, TM6SF2, CILP2, PBX4, SUGP1 and MAU2 were substantially different between the hyperlipidemia and normal groups." (PMID 32568739, 2020). "The incidences of the NCAN C-C (G2), TM6SF2 T-A (G3), TM6SF2 C-A (G5), CILP2 G-T (G6), PBX4-SUGP1 G-C (G8), MAU2 G-G-G-C (G9), MAU2 G-A-G-C (G10), MAU2 C-G-A-T (G12), and MAU2 C-A-G-T (G13) haplotypes were significantly different between the hyperlipidemia and normal groups (P < 0.05 for all)." (PMID 32568739, 2020).
Impaired glucose tolerance (3 papers, 2019 to 2024). An abnormal resistance to glucose, i.e., a reduction in the ability to maintain glucose levels in the blood stream within normal limits following oral or intravenous administration of glucose. "Elevated levels of CILP2 are a significant indicator of impaired glucose tolerance and are predominantly expressed in skeletal muscle." (PMID 39385717, 2024). "CILP-2 overexpression resulted in impaired glucose tolerance and hepatic IR in vivo and increased PEPCK expression whereas suppressed phosphorylation of insulin receptor and Akt kinase in vitro." (PMID 30896018, 2019). "We then analyzed the circulating CILP-2 levels in healthy and impaired glucose tolerance (IGT) individuals as well as newly diagnosed T2DM patients (nT2DM)." (PMID 30896018, 2019).
atherosclerosis (2 papers, 2020 to 2022). A disease characterized by the build-up of fatty material and calcium deposition in the arterial wall resulting in partial or complete occlusion of the arterial lumen. "Although these results cannot prove causality between CILP2 and atherosclerosis, credible assumptions can be made and confirmed by future prospective cohort and mechanism studies." (PMID 33204392, 2020). "To investigate whether CILP2 was associated with atherosclerosis, we examined the CILP2 expression in the aorta samples and circulating CILP2 levels in ApoE KO mice, a well-characterized animal model of atherosclerosis." (PMID 33204392, 2020). "Our data further suggest the pathogenic relevance between CILP2 and atherosclerosis." (PMID 33204392, 2020). "To further understand the relationship between CILP2 and cholesterol metabolism and atherosclerosis, we reported serum CILP2 concentrations in CHD patients and normal adults." (PMID 33204392, 2020). "Given the fact that CD36 is associated with the formation of foam cell and atherosclerosis, overexpression of CD36 and the increase of oxLDL uptake mediated by CILP2 are likely promoting atherosclerosis." (PMID 33204392, 2020). "Similar to the observation in humans, the mRNA and protein levels of CILP2 in the aorta samples of ApoE KO mice were significantly higher than in those of control mice, further confirming that CILP2 is related to atherosclerosis." (PMID 33204392, 2020). "Furthermore, we examined the possible role of CILP2 on atherosclerosis through both clinical studies and experiments in vivo and in vitro." (PMID 33204392, 2020). "However, importantly, we have also shown that serum CILP2 concentration was significantly higher in newly diagnosed patients with CHD, suggesting that CILP2 might be associated with atherosclerosis." (PMID 33204392, 2020). "However, to our knowledge, there have been no reports showing the association between CILP2 and atherosclerosis in either humans or animals." (PMID 33204392, 2020).
fibrosis (2 papers, 2021 to 2024). the formation of excess fibrous connective tissue in an organ or tissue in a reparative or reactive process. "The CILP2 protein, also known as osteoglycin, attenuates cardiac fibrosis by suppressing cardiac myofibroblast proliferation." (PMID 39768140, 2024). "As a result, P6 (CILP2) may be selected as an efficient biomarker to distinguish fibrosis patients from healthy people." (PMID 34877354, 2021).
non-alcoholic fatty liver disease (2 papers, 2016 to 2020). "In addition to plasma lipid levels, the genome region around CILP2 was identified as a non-alcoholic fatty liver disease (NAFLD)-associated locus by GWAS in individuals of European descent, but not in Japanese individuals." (PMID 33099318, 2020). "The Neurocan-cartilage intermediate layer protein 2 (NCAN-CILP2) region forms a tight linkage disequilibrium (LD) block and is associated with plasma lipid levels and non-alcoholic fatty liver disease (NAFLD) in individuals of European descent but not in the Malay and Japanese ethnic groups." (PMID 26758378, 2016).
osteosarcoma (2 papers, 2020 to 2024). A usually aggressive malignant bone-forming mesenchymal neoplasm, predominantly affecting adolescents and young adults. "Besides, few reports have described the relationship between CILP2 and cancers, except one that reported an expression quantitative trait locus, namely rs8103992, was statistically significantly associated with osteosarcoma risk." (PMID 33099318, 2020).